SMCR8 (SMCR8-C9orf72 complex subunit)
Description:
Component of the C9orf72-SMCR8 complex, a complex that has guanine nucleotide exchange factor (GEF) activity and regulates autophagy. In the complex, C9orf72 and SMCR8 probably constitute the catalytic subunits that promote the exchange of GDP to GTP, converting inactive GDP-bound RAB8A and RAB39B into their active GTP-bound form, thereby promoting autophagosome maturation. The C9orf72-SMCR8 complex also acts as a negative regulator of autophagy initiation by interacting with the ULK1/ATG1 kinase complex and inhibiting its protein kinase activity. As part of the C9orf72-SMCR8 complex, stimulates RAB8A and RAB11A GTPase activity in vitro. Acts as a regulator of mTORC1 signaling by promoting phosphorylation of mTORC1 substrates. In addition to its activity in the cytoplasm within the C9orf72-SMCR8 complex, SMCR8 also localizes in the nucleus, where it associates with chromatin and negatively regulates expression of suppresses ULK1 and WIPI2 genes.
Synonyms: FLJ34716; DENND8A
Tractability: Small molecule: a structure with a bound ligand is known. PROTAC: ubiquitination databases record sites on it; its protein half-life has been measured.
Gene: Protein-coding gene on chromosome 17 (18,315,293 to 18,328,056, forward strand). Ensembl gene ENSG00000176994.
Subcellular location: Cytoplasm; Nucleus; Presynapse; Postsynapse
Subcellular location (Human Protein Atlas): Nucleoplasm
Gene Ontology:
Molecular function: GTPase activator activity; guanyl-nucleotide exchange factor activity; protein binding; protein kinase binding; protein kinase inhibitor activity
Biological process: negative regulation of autophagosome assembly; negative regulation of gene expression; negative regulation of macroautophagy; positive regulation of autophagosome maturation; positive regulation of TOR signaling; regulation of autophagy; regulation of TORC1 signaling; negative regulation of exocytosis; negative regulation of immune response
Cellular component: Atg1/ULK1 kinase complex; chromatin; cytoplasm; guanyl-nucleotide exchange factor complex; nucleoplasm; nucleus; postsynapse; presynapse
Genetic constraint (gnomAD): Loss-of-function variants: 30 observed, 59.49 expected, observed/expected ratio (o/e) 0.5, 90% interval 0.38 to 0.68. The upper end of that interval is the gene's LOEUF score, 0.68, which puts it in group 2 of 6, group 1 being the genes least tolerant of losing a copy. Missense variants: 1,198 observed, 1,223 expected, observed/expected ratio (o/e) 0.98, 90% interval 0.93 to 1.03. Synonymous variants: 538 observed, 485.65 expected, observed/expected ratio (o/e) 1.11, 90% interval 1.03 to 1.19.
Homologues: Orthologues: chimpanzee SMCR8 (99% identical), macaque SMCR8 (98% identical), dog SMCR8 (91% identical), guinea pig SMCR8 (91% identical), rat Smcr8 (90% identical), mouse Smcr8 (90% identical), pig SMCR8 (85% identical), rabbit SMCR8 (84% identical), tropical clawed frog smcr8 (60% identical), zebrafish smcr8a (51% identical), Caenorhabditis elegans smcr-8 (14% identical).
Diseases named in the same sentence as SMCR8 in open-access papers:
SMCR8 is named in the same sentence as 23 diseases in open-access papers, as found by Europe PMC text mining. Sharing a sentence is not in itself a finding about the gene and the disease. The quoted sentences say what the papers report.
Smith-Magenis syndrome (5 papers, 2016 to 2022). Smith-Magenis syndrome (SMS) is a complex genetic disorder characterized by variable intellectual deficit, sleep disturbance, craniofacial and skeletal anomalies, psychiatric disorders, and speech and motor delay. "A variant within the SMCR8 gene in the Smith-Magenis Syndrome region was also inherited from the grandmother." (PMID 27120335, 2016). "In another example, Smith-Magenis Syndrome Chromosomal Region Candidate Gene 8 (SMCR8) forms the heterotrimer C9orf72-SMCR8-WDR41 complex (3 protein members in CORUM) together with the C9orf72-SMCR8 Complex Subunit (C9orf72) and WD Repeat Domain 41 (WDR41)." (PMID 36356032, 2022). "A series of studies have shown that the long isoform of human C9orf72 protein forms a complex with SMCR8 (Smith-Magenis Syndrome Chromosome Region, Candidate 8) and WDR41 (WD Repeat domain 41) proteins." (PMID 32678027, 2020). "The SMCR8 gene is within the deleted region of chromosome 17 associated with Smith-Magenis Syndrome (SMS), a developmental disorder of children involving intellectual disability, distinctive facial features, and behavioral problems, but no reported motor defects." (PMID 32678027, 2020). "The C9orf72 gene product forms a complex with SMCR8 (Smith-Magenis Syndrome Chromosome Region, Candidate 8) and WDR41 (WD Repeat domain 41) proteins." (PMID 32678027, 2020). "We found altered expression of 13 genes involved in the regulation of autophagy including both CALCOCO2 and Smith-Magenis syndrome chromosome region, candidate 8 (SMCR8), which are both genes that participate in most of the autophagy stages." (PMID 31009519, 2019). "Variants in the SMCR8 gene (Smith-Magenis Syndrome Chromosome Region, candidate 8; no OMIM #) and the GLP2R (Glucagon-Like Peptide 2 Receptor, OMIM #603659)) gene also showed increased LOD scores when the grandmother was coded as affected." (PMID 27120335, 2016).
Autoimmunity (3 papers, 2018 to 2023). The occurrence of an immune reaction against the organism's own cells or tissues. "Most importantly, the study of SMCR8 knockout mice has revealed that they develop autoimmunity similarly to C9ORF72 deficient animals, but they also display mild motor phenotypes resembling those observed in C9ORF72 knockout mice and in our model." (PMID 37138765, 2023). "To study the organismal and cellular functions for this tripartite complex, we generated Smcr8 loss-of-function mutant mice and found that they developed phenotypes also observed in C9orf72 loss-of-function animals, including autoimmunity." (PMID 29950492, 2018). "In addition, we produced Smcr8 loss-of-function mutant mice and found that they exhibited central phenotypes observed in C9orf72 mutant animals, including autoimmunity." (PMID 29950492, 2018). "Overall, our findings demonstrate that C9ORF72 and SMCR8 have interdependent functions in suppressing autoimmunity as well as negatively regulating lysosomal exocytosis—processes of potential importance to ALS." (PMID 29950492, 2018). "As it has been shown that C9orf72−/− mice developed autoimmunity, we first looked for signs of autoimmunity in the Smcr8 mutant mice." (PMID 29950492, 2018). "In SMCR8 and in C9ORF72 deficient mice, promoting autophagy via MTOR inhibition could rescue the autoimmunity phenotype, definitely establishing a causative link between the cellular function of C9ORF72 and immune dysfunction." (PMID 37138765, 2023). "While gene-editing approaches can have off-target effects, our findings would seem to resolve any lingering doubt concerning whether C9orf72 and its molecular collaborator, Smcr8, normally function to suppress autoimmunity." (PMID 29950492, 2018). "Therefore, we concluded that, similar to previous observations in C9orf72 mutant animals, autoimmunity was the most probable underlying cause of enlarged lymph nodes and splenomegaly seen in the Smcr8 CRISPR F0 mice." (PMID 29950492, 2018).
anemia (1 paper, 2018). A reduction in the number of red blood cells, the amount of hemoglobin, and/or the volume of packed red blood cells. "Therefore, loss of Smcr8 led to changes in peripheral blood cell composition that were indistinguishable from those observed in the C9orf72−/− mice, including anemia, thrombocytopenia, and neutrophilia." (PMID 29950492, 2018). "In total, these observations are consistent with Smcr8−/− animals developing a microcytic anemia similar to that found in C9orf72 mutant animals." (PMID 29950492, 2018).
autoimmune disease (1 paper, 2018). A disorder resulting from loss of function or tissue destruction of an organ or multiple organs, arising from humoral or cellular immune responses of the individual to their own tissue constituents. "Our finding that C9orf72 and Smcr8 mutually stabilize one another provided a key opportunity to resolve whether removing the function of this complex was indeed sufficient to lead to inflammatory and autoimmune disease." (PMID 29950492, 2018).
colitis (1 paper, 2025). Inflammation of the colon. "Smcr8 loss in mice revealed enhanced susceptibility to DSS‐induced colitis." (PMID 39873292, 2025).
lateral sclerosis (1 paper, 2023). Primary lateral sclerosis (PLS) is an idiopathic non-familial motor neuron disease characterized by slowly progressive upper motor neuron dysfunction leading to spasticity, mild weakness in voluntary muscle movement, hyperreflexia, and loss of motor speech production. "(This would be analogous to the mutually increased stability in complex shown by amyotrophic lateral sclerosis-related proteins SMCR8 and C9ORF72, as previously reported by ourselves and others)." (PMID 37405998, 2023).
Leukoencephalopathy (1 paper, 2024). This term describes abnormality of the white matter of the cerebrum resulting from damage to the myelin sheaths of nerve cells. "In our analyses, TREM2, TYROBP, and GRN associated with leukoencephalopathy and FTD, show correlated gene expression, however, SMCR8 and WDR41, known to form a complex with C9orf72, did not." (PMID 38469573, 2024).
lymphoma (1 paper, 2018). A malignant (clonal) proliferation of B- lymphocytes or T- lymphocytes which involves the lymph nodes, bone marrow and/or extranodal sites. "Our results indicated that the splenic cellular expansion in Smcr8 mutant mice was polyclonal in nature, which was not consistent with lymphoma." (PMID 29950492, 2018).
motor neuron disease (1 paper, 2020). "Finally, a recent RNA-Seq study comparing C9 FTLD and FTLD/motor neuron disease patients with unaffected control individuals reported a highly significant decrease in C9orf72 RNA levels in C9 FTLD samples; however, this data showed no significant change in SMCR8 or WDR41 RNA expression." (PMID 32678027, 2020).
neoplasia (2 papers, 2020 to 2024). "Because previous publications implicated C9orf72 protein expression in the metabolism of SGs, we wished to determine if the C9orf72 binding partner SMCR8 associates with SGs in various tumor cell lines." (PMID 32678027, 2020).
neurological disease (1 paper, 2020). "SMCR8 protein associates with many products of genes associated with various Mendelian neurological disorders in addition to ALS, implicating SMCR8-containing complexes in a range of neuropathologies." (PMID 32678027, 2020).
SMCR8 also shares sentences with these, for which no sentence is quoted: amyotrophic lateral sclerosis (7 papers); frontotemporal dementia (4); neurodegenerative disease (3); asthma (1); Cornelia de Lange syndrome (1); familial amyotrophic lateral sclerosis (1); immune dysfunction (1); Intellectual disability (1); neuroblastoma (1); neurofibromatosis (1); Splenomegaly (1); Thrombocytopenia (1).